CEBPD (CCAAT enhancer binding protein delta)
Diseases named in the same sentence as CEBPD in open-access papers (continued):
Sharing a sentence is not in itself a finding about the gene and the disease.
psoriasis (4 papers, 2022 to 2025). An autoimmune condition characterized by red, well-delineated plaques with silvery scales that are usually on the extensor surfaces and scalp. "Shikonin is a 288-kDa liposoluble naphthoquinone derived from Lithospermum erythrorhizon, which could suppress IL-17-induced production of cytokines associated with psoriasis by inhibiting the JAK/STAT3 signaling pathway and suppression of CEBPD downregulation." (PMID 35485255, 2022). "In HaCaT cells and an IMQ-induced psoriasis mouse model, shikonin restored tumor suppressor CCAAT/enhancer-binding protein δ (CEBPD) expression." (PMID 38892253, 2024).
amyotrophic lateral sclerosis (3 papers, 2015 to 2022). Amyotrophic lateral sclerosis (ALS) is a neurodegenerative disease characterized by progressive muscular paralysis reflecting degeneration of motor neurons in the primary motor cortex, corticospinal tracts, brainstem and spinal cord. "Of these, CEBPD has been reported to be a biomarker for amyotrophic lateral sclerosis." (PMID 36419834, 2022).
bladder cancer (3 papers, 2019 to 2021). "On the other hand, recent studies imply that CEBPD plays a pro-tumorigenic role in drug resistance and cell invasion in bladder cancer." (PMID 31300060, 2019). "CCAAT/enhancer-binding protein delta (CEBPD) was reported to be inducible by CDDP and led to chemoresistance in bladder cancer." (PMID 32661323, 2020).
Hypertension (3 papers, 2014 to 2022). The presence of chronic increased pressure in the systemic arterial system. "Here, we found the significant association of ADM, EDN1, ANGPTL4, USP8, NFIL3, MSR1, and CEBPD genes with hypertension." (PMID 35205232, 2022). "We observed that macrophage scavenger receptor 1 (MSR1) and CEBPD are downregulated in hypertension cases compared to control." (PMID 35205232, 2022). "Moreover, CEBPD has a facilitatory role in binding with other transcription factors and contributes to the vibrant alteration of the chromatin architecture, with recognized effects in hypertension." (PMID 35205232, 2022). "From 50 DEGs, we ranked 7 hypertension-related genes (p-value < 0.05): ADM, ANGPTL4, USP8, EDN, NFIL3, MSR1, and CEBPD." (PMID 35205232, 2022). "ADM, EDN1, ANGPTL4, NFIL3, MSR1, CEBPD, and USP8, based on their FDR values (<0.05, p-values (≤0.05)), were the top DEGs for hypertension." (PMID 35205232, 2022). "‘Unknown I’ contained a diverse set of key driver genes such as SGK1, SIK1 and SLC10A6 (sodium metabolism and hypertension), MT2A and TSC22D3 (glucocorticoid signaling), GADD45G, ERRFI1, GPRC5A, and EGFR (cell growth and apoptosis), and CEBPB, CEBPD, and KCNA5 (heart development and function)." (PMID 25033284, 2014).
Arthritis (2 papers, 2022). Inflammation of a joint. "For example, CEBPD-deficient-collagen-induced arthritis mouse models had a lower RA activity compared to the wild type, whilst knockout of CEBPD in dextran-sulfate sodium (DSS)-induced colitis mice resulted in a higher susceptibility to the disease." (PMID 35627163, 2022).
autoimmune disease (2 papers, 2022). A disorder resulting from loss of function or tissue destruction of an organ or multiple organs, arising from humoral or cellular immune responses of the individual to their own tissue constituents. "CEBPD changes the Th17/Treg balance in an IL-10-dependent manner, and it plays a functional role in dendritic cells and central nervous system autoimmune diseases." (PMID 35204186, 2022). "CEBPD is a transcription factor that forms a heterodimer with CEBPB (PPi score = 0.991), which further regulates the transcription of IL-6, a key proinflammatory cytokine overexpressed in multiple autoimmune diseases." (PMID 35627163, 2022).
Cachexia (2 papers, 2011 to 2022). Severe weight loss, wasting of muscle, loss of appetite, and general debility related to a chronic disease. "We also observed a clear decrease in genes dominantly regulating fat cell differentiation, including CEBPB, CEBPD, BMP2, and KLF4, in vPreA in cachexia group, as compared to patients without cachexia." (PMID 36376273, 2022).
cholangiocarcinoma (2 papers, 2020 to 2021). A carcinoma that arises from the intrahepatic biliary tree (intrahepatic cholangiocarcinoma) or from the junction, or adjacent to the junction, of the right and left hepatic ducts (hilar cholangiocarcinoma). "Among the 20 upregulated transcription factors, CEBPD, CSRNP1, and KLF10 were regularly underexpressed in cholangiocarcinoma but upregulated by PDT treatment." (PMID 34805140, 2021).
liposarcoma (2 papers, 2008 to 2022). A usually painless malignant tumor that arises from adipose tissue. "Although CEBPB and CEBPD are expressed early in adipogenesis and promote PPARG2 mRNA expression, induction of either gene is insufficient to drive PPARG2 mRNA upregulation in the liposarcoma tissues in the absence of ZFP423 protein." (PMID 35313831, 2022).
lymph node metastases (2 papers, 2020 to 2021). "A clinicopathologic association study in patients with GBC demonstrated that high expression of pSTAT3, CEBPD, and MCL1 was significantly associated with advanced clinical stages, tumor grades, and lymph node metastasis." (PMID 34156978, 2021).
myeloma (2 papers, 2007 to 2021). "Some of these TFs were specifically downregulated in MSCs of active myeloma (RUNX2 and TEAD2), others were already downregulated in precursor myeloma stages (HOXC9 and CEBPD), whereas other TFs, including HOXA2 and ATF3, did not change their expression in any myeloma stages." (PMID 33462210, 2021).
neuroblastoma (2 papers, 2015 to 2023). Neuroblastoma (NB) is the most common solid, extracranial childhood tumor. "Recent studies have identified the transcription factors CEBPB and CEBPD as CP-dn-ATF5 targets, suggesting they are also potential targets for neuroblastoma." (PMID 38014922, 2023).
nonalcoholic fatty liver disease (2 papers, 2020 to 2023). "CEBPD has been identified as a diagnostic biomarker for nonalcoholic fatty liver disease using machine learning algorithms and is associated with immune cell infiltration." (PMID 36860337, 2023).
prion disease (2 papers, 2012 to 2015). A transmissible disease that is caused by a protein that is able to induce abnormal folding of normal cellular proteins, leading to characteristic spongiform brain changes, which are associated with neuronal loss without an inflammatory response. "Overexpression of the CEBPD isoform is observed in Alzheimer’s and in prion disease." (PMID 23068602, 2012).
renal carcinoma (2 papers, 2024 to 2025). A carcinoma arising from the epithelium of the renal parenchyma or the renal pelvis. "Previous studies have highlighted the downregulation of CEBPD in RCC and the association of FOS and JUNB with renal cancer." (PMID 38292868, 2024). "Co-culture experiments revealed that the increased expression of SPP1 in renal cancer cells led to a marked polarization of APOE+ M2-like macrophages, elevated the levels of immunosuppressive markers like APOE and CEBPD." (PMID 40303328, 2025).
schizophrenia (2 papers, 2010 to 2012). A major psychotic disorder characterized by abnormalities in the perception or expression of reality. "Five genes (SELL, HLA-DRB1, CEBPD, HSPA5, and NRGN) from the matched list had been previously studied for schizophrenia with positive association signals, the rest of the genes were involved in immune responses or other neuronal diseases." (PMID 23282246, 2012). "Two other CNS-related candidate genes, CEBPD and LHX5 may be associated with schizophrenia, but the results of array CGH should be treated carefully in the absence of validation by other technologies." (PMID 20064257, 2010).
steatosis (2 papers, 2023 to 2024). Increased lipid within the cytoplasm of cells. "Indeed, a markedly increased abundance of CEBPD was observed in the livers of NASH patients and HFHC/WTDF diet-treated rodent models as compared to those of non-steatosis donors and NCD diet-fed control mice." (PMID 37821436, 2023).
Stroke (2 papers, 2013 to 2025). Sudden impairment of blood flow to a part of the brain due to occlusion or rupture of an artery to the brain. "Downregulating CEBPD can lead to reduced neurofunctional deficits, smaller infarct sizes, improved cell survival, and decreased apoptosis and oxidative stress both in vivo and in vitro, suggesting that CEBPD could be a new target for stroke treatment." (PMID 41021615, 2025).
triple-negative breast carcinoma (2 papers, 2021 to 2024). An invasive breast carcinoma which is negative for expression of estrogen receptor (ER), progesterone receptor (PR), and human epidermal growth factor receptor 2 (HER2). "This study investigates the involvements of a CCAAT enhancer binding protein delta (CEBPD)/vesicle associated membrane protein 3 (VAMP3) axis in paclitaxel (PTX) resistance and immune evasion in triple-negative breast cancer (TNBC)." (PMID 38627816, 2024).
viral infection (2 papers, 2019 to 2023). "Interestingly, transcriptional regulation of CEBPB and CEBPD in humans and macaques, but not mouse cells stimulated with double-stranded RNA, which mimics a viral infection, were also observed in an independent data set." (PMID 31637998, 2019).
abdominal aortic aneurysm (1 paper, 2025). Enlargement and ballooning of the vessel that supplies arterial blood to the abdomen, pelvis and legs. "A recent report showed that CEBPD is significantly upregulated in abdominal aortic aneurysm and that increased CEBPD promotes macrophage polarization toward M1 and maintains the M1 inflammatory state, accelerating abdominal aortic aneurysm progression." (PMID 40087290, 2025).
alcohol dependence (1 paper, 2019). Physical and psychological dependence on alcohol. "Immunohistochemistry results support the hypothesis of alcohol-induced neuroinflammation and pose interesting questions concerning the role of CEBPD signaling in alcohol dependence." (PMID 31358844, 2019).
Allergy (1 paper, 2022). An allergy is an immune response or reaction to substances that are usually not harmful. "In addition, we showed that, upon PTX3 treatment, CEBPD is activated in mast cells and participates in shrimp allergy." (PMID 36530573, 2022). "The results prompted us to further examine whether CEBPD is activated by PTX3 and contributes to shrimp allergy." (PMID 36530573, 2022). "Surprisingly, the PTX3 concentration was still significantly high in the serum during the hypersensitization phase in Cebpd−/− mice, implying that PTX3 may not be regulated by CEBPD in shrimp allergy." (PMID 36530573, 2022).
asthma (1 paper, 2022). "We sought to characterize CEBPD-mediated transcriptomic responses to glucocorticoid exposure in ASM by measuring changes observed after knockdown of CEBPD and its impact on asthma-related ASM function." (PMID 35902923, 2022). "Of relevance to asthma, expression of CEBPD in airway smooth muscle (ASM) increases with glucocorticoid exposure." (PMID 35902923, 2022). "Further mechanistic insights regarding these CEBPD-mediated ASM transcriptomic changes may lead to an improved understanding of glucocorticoid responses in patients with asthma." (PMID 35902923, 2022). "Future studies are needed to investigate more detailed mechanisms whereby altered CEBPD expression and its posttranslational modifications affect IL-6R signaling in ASM to influence glucocorticoid responses in asthma." (PMID 35902923, 2022).
bipolar disorder (1 paper, 2024). A disorder of the brain that causes unusual shifts in mood, energy, activity levels and the ability to carry out day-to-day tasks. "This study represents the initial investigation into the role of CEBPD in the development of manic-like symptoms in bipolar disorder, particularly its impact on manic behavior." (PMID 38419037, 2024).
Burkitt lymphoma (1 paper, 2020). A rare form of malignant mature B-cell non-Hodgkin lymphoma. "Little is known about the role of CEBPD in B cells, but it is mutated in a Burkitt lymphoma cell line, pointing to a potential role in B cell malignancies." (PMID 32316399, 2020).
cervical dysplasia (1 paper, 2021). "Five out of ten consistently upregulated genes (CEBPD, KRT16, SLPI, RPS29, and PPL) were also increased in cervical dysplasia." (PMID 34944802, 2021). "Unlike CEBPD, SLPI, KRT16, and RPS29, NOTCH1 expression in these cell lines did not match the increase seen in cervical dysplasia and cancer samples in silico." (PMID 34944802, 2021).
chordoma (1 paper, 2016). Chordomas are rare malignant tumors arising from embryonic remnants of the notochord in axial skeleton. "This suggests that CEBPD is potentially involved in the pathway of IFN-γ-induced PD-L1 expression in chordoma cells." (PMID 27172898, 2016). "Further investigation is needed to confirm the function of CEBPD in chordoma cells." (PMID 27172898, 2016).
clear cell renal cell carcinoma (1 paper, 2025). "In clear cell renal cell carcinoma, the transcription factor CEBPD, which regulates TAM polarization, is linked to a decreased anti-tumoral/pro-tumoral ratio and worse clinical outcomes." (PMID 41417432, 2025).
dyslipidemia (1 paper, 2025). "In contrast, various injury stimuli, such as transverse aortic constriction (TAC), MI, and dyslipidemia can significantly induce CEBPD expression in myocardial and vascular tissues, suggesting that CEBPD mainly responds to pathological stimuli." (PMID 40087290, 2025).
E. coli infection (1 paper, 2009). "Our QTL analyses showed that CEBPD may also be linked to ECF18R, a crucial protein that counteracts E. coli infection in young piglets, which indicates its important role in innate immunity." (PMID 19196461, 2009).
endometriosis (1 paper, 2024). The growth of functional endometrial tissue in anatomic sites outside the uterine body. "In the uM1 population, a significant increase in expression of inflammatory genes (TNFRSF1B, CEBPD) was detected in endometriosis, in keeping with previous reports of increased inflammation in endometriosis." (PMID 39198675, 2024).
gallbladder cancer (1 paper, 2024). "In gallbladder cancer, CEBPD activated myeloid cell leukemia 1 transcription to prevent tumor cells from stress-induced death." (PMID 38627816, 2024).
Granuloma (1 paper, 2026). A compact, organized collection of mature mononuclear phagocytes, which may be but is not necessarily accompanied by accessory features such as necrosis. "We found that 7 of the top 10 unique marker genes associated with the activated neutrophils were significantly upregulated in LN granuloma compared with noninfected LN controls, as well as the pro-inflammatory markers CEBPD and LDHA." (PMID 41489684, 2026).
Hepatic steatosis (1 paper, 2023). Steatosis is a term used to denote lipid accumulation within hepatocytes. "Furthermore, in keeping with its pro-inflammatory effects in vitro, CEBPD also plays a critical role in the progression of hepatic steatosis, including the regulation of liver inflammation and lipid metabolism." (PMID 37821436, 2023).
kidney cancer (1 paper, 2023). Primary or metastatic malignant neoplasm involving the kidney. "Interestingly, among the top co-upregulated TFs in kidney cancer, we prioritized the MYC proto-oncogene, CCAAT Enhancer Binding Protein Data (CEBPD) and RELA proto-oncogene, NK-kB subunit (RELA)." (PMID 37047552, 2023).
kidney stones (1 paper, 2025). "We found that after kidney stone treatment, the expression of S100A4, ARPC1B, and CEBPD genes in diabetic mice was significantly elevated." (PMID 40718484, 2025).
myocardial infarction (1 paper, 2025). Gross necrosis of the myocardium, as a result of interruption of the blood supply to the area, as in coronary thrombosis. "Upregulation of CEBPD in the epicardial cells of the heart caused by myocardial infarction (MI) promotes heart regeneration in zebrafish." (PMID 40087290, 2025).
nervous system injuries (1 paper, 2024). "CCAAT/Enhancer-Binding Protein Delta (CEBPD) is an inflammatory transcription factor associated with the progression of neurological diseases, including neurodegenerative diseases and central nervous system injuries." (PMID 38419037, 2024).
osteoporosis (1 paper, 2025). A condition of reduced bone mass, with decreased cortical thickness and a decrease in the number and size of the trabeculae of cancellous bone (but normal chemical composition), resulting in increased fracture incidence. "In this section, we discuss the role of macrophage CEBPD in lung disease, osteoporosis, RA, vascular disease, and tumor biology." (PMID 40990024, 2025).
papillary thyroid carcinoma (1 paper, 2023). "Moreover, CCAAT enhancer-binding protein delta was negatively regulated in papillary thyroid carcinoma via miR-324-5p targeting of protein tyrosine phosphatase receptor delta." (PMID 37036350, 2023).
Primary immunodeficiency (1 paper, 2024). "For instance, CTSD is involved in the pathways of ‘Notch signaling pathway,’ CEBPD and CYP27A1 simultaneously mediate ‘T cell receptor signaling pathway,’ ‘Primary immunodeficiency’ and ‘bacterial infection’ signal pathways." (PMID 38451044, 2024).
primary Sjogren's syndrome (1 paper, 2024). "It has also been found that CEBPD is highly expressed in CD14(+) monocytes from patients with primary Sjogren's syndrome, and is involved in the TNF-α signaling pathway through NF-κB30." (PMID 38890389, 2024).
prosaposin deficiency (1 paper, 2008). "CEBPD is apparently a candidate regulator participated in disease progression in prosaposin deficiency." (PMID 18673548, 2008).